MTOR (mechanistic target of rapamycin kinase)
Diseases named in the same sentence as MTOR in open-access papers (continued):
Sharing a sentence is not in itself a finding about the gene and the disease.
lung cancer (continued). "Additionally, MetaLnc9 facilitates metastasis of lung carcinoma by sensitizing cells to the AKT/mTOR signaling pathway." (PMID 34235076, 2021). "The anti‐lung cancer effect of LA was mediated through the mTOR‐mediated inhibition of autophagy." (PMID 32090494, 2020). "Therefore, we investigated the relationship between baicalin-induced anti-proliferation effects in lung cancer cells and the Akt/mTOR pathway." (PMID 33585556, 2020). "In our study, we suggested that knock-down of ZNF322A in lung cancer induces phosphorylation of IR1S that attenuates PI3K/AKT/mTOR signaling pathway, leading to glucose starvation which may trigger autophagosome formation." (PMID 32576196, 2020). "It has been confirmed by researchers that suppression of PI3K/Akt/mTOR signaling pathway activation may inhibit cells proliferation and metastasis in lung cancer." (PMID 32655659, 2020). "Indeed, it has been reported that MTOR inhibitors are effective in a subset of patients with Rictor gene amplification in lung cancer and gastric cancer." (PMID 32938364, 2020). "Altogether, the data suggest that LA exerts an anti‐lung cancer effect through mTOR‐mediated inhibition of autophagy, and thus LA may have therapeutic potential for lung cancer management." (PMID 32090494, 2020). "This anti‐lung cancer effect of LA was mediated by the mTOR‐mediated autophagy inhibition." (PMID 32090494, 2020). "However, the prolonged treatment of human lung cancer cells with rapalogs results in an mTOR-targeted therapy resistance through the compensatory feed-back mechanism between AKT/mTOR pathway and MNK/eIF4E pathway." (PMID 32340135, 2020). "Collectively, the findings from this study suggest that mTOR and USP7 may serve as additional novel targets for developing strategies to prevent and treat arsenic and BaP co-exposure-caused lung cancer." (PMID 32802178, 2020). "It has been reported in the previous studies that suppression PI3K/Akt/mTOR signaling pathway activation may inhibit cells proliferation and metastasis in lung cancer." (PMID 32655659, 2020). "With the in-depth study of the mechanism for driver genes in lung cancer with brain metastasis, driver gene-associated signaling pathways, such as RAS/RAF, PI3K/AKT/mTOR, WNT/β-catenin, and JAK/STAT, also provide new targets for the treatment of lung cancer with brain metastases." (PMID 33537237, 2020). "Furthermore, cardamonin reduced tumoral growth and induced apoptosis in NSCLC A549 and H460 lung cancer cells, by decreasing expression rates of Ki-67 and phosphorylated Akt and mTOR." (PMID 36046386, 2020). "Additionally, a previous study by our group showed a significant reduction of total Akt and mTOR expression by 50 μg/mL RE treatment in A549 lung cancer cells." (PMID 32012648, 2020). "In addition, some small molecular drugs targeting individual PI3K, Akt or mTOR signalling proteins or dual blockade of PI3K and mTOR have been reported to enhance radiosensitivity in prostate cancer, oral squamous cell carcinoma and lung cancer." (PMID 32239160, 2020). "Thus, inhibition of the PI3K/Akt/mTOR pathway is predicted to exert antitumor activity in lung cancer." (PMID 31262325, 2019). "By targeting c-Met/PI3k/AKT/mTOR (mammalian target of rapamycin) signaling, miR-206 inhibits the hepatocyte-growth-factor-induced epithelial-mesenchymal transition, the migration and invasion of lung cancer cells, as well as HUVEC migration and capillary tube formation." (PMID 31757094, 2019). "Similarly, several reports have shown that dual PI3K/mTOR inhibitors used as monotherapies mainly lead to cytostatic antitumor effects in lung cancer and other cancers, such as pancreatic cancer." (PMID 31262325, 2019).
lung cancer (continued). "Consistent with the previous report, TRIM44 facilitates the migration and invasion of human lung cancer cells via the NF–κB signaling pathway and in another preclinical study, while TRIM44 promotes proliferation and metastasis in non–small cell lung cancer via mTOR signaling pathway." (PMID 30792262, 2019). "In addition, many critical literatures has been reported that ViceninII has shown anti-inflammatory effect through the inhibition of TGF-β-induced protein signaling pathway as well as induced apoptosis of lung cancer H23 cell via PI3K/Akt/mTOR signaling." (PMID 30609689, 2019). "We subsequently demonstrated that WA could inhibit the growth of lung CSCs, decrease side population cells, and inhibit lung cancer spheroid-forming capacity, at least through downregulation of mTOR/STAT3 signaling." (PMID 31319622, 2019). "Additionally, these findings highlighted the role of autophagosome activation and the related AMPK/Akt/mTOR pathways and apoptosis, thereby providing new ideas for the treatment of lung cancer." (PMID 31475112, 2019). "We showed that this also occurred in lung cancer cells and could be regulated by modulating specific cancer signalling pathways such as mTOR and MAPK-MNK1/2." (PMID 30845770, 2019). "IARS2 appears to regulate lung cancer cell proliferation via the AKT/MTOR pathway." (PMID 31157169, 2019). "Mito-LND blocks lung tumor development and brain metastasis by inhibiting mitochondrial bioenergetics, stimulating the formation of reactive oxygen species, oxidizing mitochondrial peroxiredoxin, inactivating AKT/mTOR/p70S6K signaling, and inducing autophagic cell death in lung cancer cells." (PMID 31101821, 2019). "We found that NDV/FMW triggered autophagy in paclitaxel-resistant A549 lung cancer cells via dampening the class I PI3K/Akt/mTOR/p70S6K pathway whereas it attenuated the autophagic process in cisplatin-resistant A549 cells through the activation of the negative regulatory pathway." (PMID 29487586, 2018). "Blocking of PI3K/Akt/mTOR by stellettin B‐induced autophagy in human non–small cell lung cancer." (PMID 29316373, 2018). "In addition, inactivated Sendai virus (HVJ-E) induced autophagy in lung cancer cells via the PI3K/Akt/mTOR/p70S6K signaling pathway, and inducing autophagy enhanced HVJ-E-induced apoptosis." (PMID 29487586, 2018). "In lung cancer, mTOR phosphorylation was found in 51% of NSCLC patients." (PMID 29464099, 2018). "PTEN and mTOR were proven to be significant regulators of autophagy in our study, but further studies are needed to provide enough evidence for clinical practice of target therapy in lung cancer." (PMID 30245856, 2018). "LF-MFs could up-regulate the expression level of miR-486 by targetting B-cell adaptor for phosphatidylinositol 3-kinase (BCAP) and further inhibiting lung cancer through miR-486-induced autophagic cell death by inhibiting AKT/mTOR signaling pathway." (PMID 30266744, 2018). "High mTOR protein expression levels have been detected in non‐small cell lung cancer (NSCLC) tissues and cell lines, and suppressing mTOR could attenuate the development of cancer." (PMID 29266795, 2018). "shRNA against SENS2 transfection was observed to increase mTOR activity in lung cancer." (PMID 29296193, 2017). "The anti-proliferative function of miR-363-3p toward lung cancer cells may be explained by its ability to inhibit the activation of the mTOR and ERK signaling pathways." (PMID 28423618, 2017). "Moreover, piR-55490 was shown to function as a potent tumor suppressor by inducing degradation of mTOR mRNA in a miRNA-like manner and thereby suppressing the activation of the Akt/mTOR pathway, leading to inhibition of lung cancer cell proliferation." (PMID 28460486, 2017). "Dysregulation of mTOR signaling is reported in several malignancies, including lung cancer." (PMID 29234489, 2017).
lung cancer (continued). "The present study was undertaken to gain insight into the mechanism by which AQR could arise following the application of PI3K/mTOR inhibitors to EGFR inhibitor-refractory lung cancer." (PMID 29299135, 2017). "It was reported that BMP2 induces the phosphorylation of mTOR and p70S6 kinase in lung cancer cell lines through a Smad 1/5–independent mechanism and promotes motility and invasion of chondrosarcoma cells, gastric cancer cells and pancreatic cancer cells by activating PI3K/Akt signaling pathway." (PMID 28455969, 2017). "It has been reported that the VEGF/VEGFR-2 feed-forward loop increases VEGF secretion in lung cancer via mTOR-dependent regulation that is required for the activation of downstream signaling, and the over-expression of VEGFR-1 reduces EGFR-TKIs sensitivity in different human cancer cells." (PMID 28288164, 2017). "A synergistic effect of a combined treatment with 2-DG and PI3K/mTOR inhibitors as found in our experiments has already been described by a few authors: In lung cancer cell lines, an analogue of Rapamycin hypersensitized cells to 2-DG treatment under hypoxic conditions." (PMID 28724379, 2017). "In this study, we revealed that enhanced expression of miR-206 could reverse HGF-induced EMT and angiogenesis in lung cancer through inhibiting c-Met/Akt/mTOR pathway." (PMID 26919096, 2016). "In order to investigate whether combined targeting mTOR and Mnk/eIF4E pathway would result in augmenting growth-inhibitory effects on lung cancer cells, four human NSCLC cell lines were treated by RAD001 alone or in combination with CGP57380." (PMID 27050281, 2016). "It would be of interest to investigate whether Rab1B, a paralog of Rab1A, could play a major role in mTOR regulation in lung cancer." (PMID 27902464, 2016). "Additionally, increased mTOR expression was correlated with a poor prognosis in several human cancers, including renal cell cancer, lung cancer, laryngeal squamous cell carcinoma, neuroendocrine tumors, biliary tract adenocarcinoma, and colorectal cancers." (PMID 27533457, 2016). "Several studies could show that mutant NRAS activates the PI3K/mechanistic target of rapamycin (mTOR)-signaling cascade in melanoma and lung cancer." (PMID 26821351, 2016). "Our results indicate that ZNF703 is a new candidate gene in lung cancer and may contribute to the development of lung tumors by activating the Akt/mTOR pathway." (PMID 27650486, 2016). "We discovered that (ruxolitinib + afatinib) treatment reduced mTOR phosphorylation at both S2448 and S2481 in multiple breast and lung cancer cell lines, including the NSCLC PDX isolate ADOR, arguing that our drug combination was inactivating both the mTORC1 and mTORC2 signaling complexes." (PMID 27379204, 2016). "There was a extensively accepted mechanism of metformin action that metformin could activate the LKB1/AMPK signal axis in lung cancer cell, subsequently resulting in reduced cancer cell growth and proliferation via the suppression of mTOR activity." (PMID 27105507, 2016). "Therefore, HMGA1, a regulator of the PI3K/AKT/mTOR pathway, is a potential target for lung cancer treatment." (PMID 27602961, 2016). "As an FDA-approved drug with documented pharmacokinetic and safety profiles in humans, and having potent inhibitory effects in multiple sites of the PI3K/ATK/mTOR axis in human lung cancer cells, auranofin is likely for rapid clinical translation of its new application for lung cancer therapy." (PMID 26657290, 2016). "We therefore examined Akt-mTOR and Erk activation in lung cancer cells with ONC201 treatment." (PMID 27626799, 2016). "Moreover, it has been demonstrated that the glutamate-transporter SLC1A5 is essential for cell growth in lung cancer and that the intake of L-glutamine regulates mTOR signalling." (PMID 25415227, 2015).
lung cancer (continued). "Caspase-9 was activated in A549 cells after treatment with AZD2014 or AZD2014 combined with 2DG, suggesting the involvement of mitochondrial apoptotic pathway in the apoptosis induced by mTOR inhibitor alone and combined with glycolysis inhibitor in lung cancer cells." (PMID 26176608, 2015). "We then asked if the inhibition of glycolysis could enhance apoptosis induced by mTOR inhibitors in lung cancer cells." (PMID 26176608, 2015). "Moreover, autophagosome accumulation has been shown to induce autophagic cell death via Akt/mTOR pathway in a GMI-treated lung cancer cell model." (PMID 25946033, 2015). "Besides Src, the mammalian target of rapamycin (mTOR) is also highly activated in many lung cancer patients and represents as another target for therapy." (PMID 26061184, 2015). "A549 lung carcinoma cells in contrast do not have any known mutations in the PI3K/mTOR pathway, but a mutation in the Kirsten rat sarcoma viral oncogene homolog (KRAS) gene, which occurs in about 30 % of non small cell lung cancers." (PMID 26498922, 2015). "We could show that the TSC tumor suppressor complex is substantially expressed in lung cancer cell lines and that hamartin and p-mTOR were inversely correlated in three of the five lung cancer cell lines." (PMID 24593867, 2014). "Numerous mTOR inhibitors have been revealed to provide antitumor effects in lung cancer." (PMID 25360163, 2014). "Furthermore, preclinical data suggests that this class of mTOR pathway antagonists exert an antitumor effect in lung cancer therapy." (PMID 25360163, 2014). "Irrespective of the mechanism, the frequent enhancement of PI3K/Akt/mTOR activation suggests in lung cancer suggests an important role for the pathway in carcinogenesis, thus providing strong impetus for the development of targeted agents directed at inhibiting the PI3K/Akt/mTOR pathway." (PMID 25221647, 2014). "We next evaluated whether mTOR inhibitors would control the growth of EGFR mutant lung cancer cells with HGF-triggered EGFR-TKI-resistance in vivo." (PMID 23690929, 2013). "In addition, recent preclinical studies have shown that dual inhibition of mTOR with rapamycin and Akt with perifosine prevents mTOR inhibition-initiated Akt activation and significantly enhances antitumor effects in lung cancer and multiple myeloma." (PMID 23663564, 2013). "The PI3K/AKT/mTOR pathway contributes to the survival of EGFR mutant lung cancer cells." (PMID 23690929, 2013). "Combined Bcl-2/mTOR inhibition was observed to lead to enhanced radiosensitivity via induction of apoptosis and autophagy in vitro and in a lung cancer xenograft model; this is a potential therapeutic strategy for enhancing radiation therapy in patients with non-small cell lung cancer." (PMID 23760551, 2013). "Based on our finding that fucoidan suppresses PI3K-Akt pathway in human lung cancer cells, it was examined whether fucoidan modulates mTOR and its downstream signaling molecules." (PMID 23226337, 2012). "This could explain how co-inhibition of MEK and mTOR synergize to inhibit protein translation and growth in certain lung cancer cells." (PMID 23085539, 2012). "Our results suggest that a therapeutic strategy combining specific inhibitor of mTOR with cytotoxic agents may be a promising approach to an improved treatment of advanced lung cancer." (PMID 21392382, 2011). "mTOR inhibitors are being investigated in clinical trials in several hematologic, gastrointestinal, genitourinary, and neurologic cancers, NETs, and sarcomas, as well as in breast and lung cancers." (PMID 21584218, 2010). "With the EGFR/PI3K signaling cascade being one of the most frequently mutated pathways in lung cancer, we speculated that combined inhibition of EGFR- and PI3K/mTOR-signaling might be effective in our cell line panel of NSCLC cells." (PMID 20111714, 2010). "Clearly, mTOR is a lung cancer target; yet, the jumble of alternate pathways raises doubts as to whether this is the primary mechanism." (PMID 18728656, 2008).
lung cancer (continued). "In addition, mTOR inhibitors in canine PC may serve as an animal model for human lung cancer research." (PMID 40563640, 2025). "Alterations in different components of the PI3K/Akt/mTOR pathway, including somatic mutations of PIK3CA, deletions of PTEN, and increased Akt activity, have been recorded in most NSCLC cases, resulting in this pathway being one of the most frequently deregulated in lung cancer." (PMID 38672636, 2024). "Consequently, in the absence of STK11, lung cancers harboring KRAS mutations not only gain a growth advantage due to the unrestrained signaling of mTOR but also exhibit mitochondrial dysfunction, resulting in aggressive behavior." (PMID 39046176, 2024). "Therefore, the interaction between Nrf2 and PI3K/AKT/mTOR signaling pathway plays a significant role in promoting the malignant progression of lung cancer, and the elevated Nrf2 expression promotes lung cancer progression and enhances the ability of tumor cells to evade apoptosis." (PMID 37810967, 2023). "A study in lung cancer revealed that fluoxetine could reduce the proliferation and induce the autophagy of tumor cells by activating the endoplasmic reticulum stress-related protein and the mTOR pathway." (PMID 36994207, 2023). "Additionally, miR-99b-5p negatively regulates mTOR and AR expression and blocks the nuclear translocation of mTOR, consequently inhibiting cell viability and enhancing docetaxel-induced cytotoxicity in PCa, breast, colon, and lung cancer cells." (PMID 37370750, 2023). "Hence, a smart combination approach can target the PI3K/AKT/mTOR pathway in lung cancer cells." (PMID 36721812, 2023). "To examine whether the ability of pharmacological VC to inhibit the mTOR pathway is unique to lung cancer cells, we also treated colon cancer cells (DLD1 and HCT116) with different concentrations of pharmacological VC and again found that S6K, S6, 4EBP1, and AKT phosphorylation were inhibited." (PMID 36787291, 2023). "Interestingly, we found that high expression levels of EGFR/MAP2K1/mTOR/TEAD1/YAP1 in lung cancer significantly decreased overall levels of active cytotoxic lymphocytes, mediated dysfunctional T-cell phenotypes, and produced worse overall survival rates of lung cancer cohorts." (PMID 35655775, 2022). "The results showed that mubritinib can reduce the activation of the PI3K/mTOR signal pathway, disrupt mitochondrial function, significantly increase ROS levels and induce oxidative stress, and ultimately exert its antitumor effect against non‐small cell lung cancer (NSCLC) both in vivo and in vitro." (PMID 35429141, 2022). "To identify potential drugs that might sensitize abemaciclib, we employed FDA-approved small-molecule protein kinase inhibitors to co-treat with abemaciclib in lung cancer cells, and found that mTOR inhibitor, rapamycin and FLT3 inhibitor, gilteritinib enhanced the cytotoxicity of abemaciclib." (PMID 35814226, 2022). "Similarly, AKT and 4EBP1, downstream targets of the PI3K/AKT/mTOR pathway, were inhibited by NT157, further highlighting the antineoplastic potential of this compound in lung cancer, since this signaling pathway is mutated or aberrantly activated in this disease." (PMID 36224313, 2022). "Besides, APS enhanced autophagy by inhibiting the PI3K/AKT/mTOR pathway, and a sulfated dextran from cinnamon could reduce the viability of lung cancer cells by inhibiting mTOR activity." (PMID 35864870, 2022). "Despite it remains the cornerstone of advanced lung cancer treatment, evidence is that many chemotherapies may drive sarcopenia via NF kappa B activation and protein kinase B (AKT)/mammalian target of rapamycin (mTOR) downregulation leading to loss of myogenesis." (PMID 33804536, 2021). "Furthermore, leptin could stimulate the proliferation of lung cancer cells in a PI3K/Akt/mTOR-dependent manner in vitro." (PMID 33708630, 2021).